FLNA (filamin A)
Diseases named in the same sentence as FLNA in open-access papers (continued):
Sharing a sentence is not in itself a finding about the gene and the disease.
peritonitis (2 papers, 2013 to 2021). Inflammation of the peritoneum (tissue that lines the abdominal wall and covers most of the organs in the abdomen). "However, in an in vivo peritonitis model, filamin A deletion impaired neutrophil chemotaxis, revealing a role of filamin A in inflammatory responses and potentially in cancer." (PMID 33573141, 2021).
psychosis (2 papers, 2024). "Interestingly, among these proteins, there were the Heparin cofactor 2, Immunoglobulin heavy constant mu, the platelet factor 4, Filamin-A and Actin, cytoplasmic 1, Thymosin beta-4 which locus maps within the deleted region of chromosome 22 and found to be strongly associated with psychosis." (PMID 38418685, 2024). "The ECM module, associated strongly with agitation and psychosis and more weakly with apathy, yielded 10 potential hub genes, including TAGLN (MFC,agitation = 0.362, p = 1.3 × 10−5) and FLNA (MFC, agitation = 0.646, p = 5.9 × 10−6)." (PMID 38575567, 2024).
Salmonella Infections (2 papers, 2023 to 2025). Infections with bacteria of the genus SALMONELLA. "ENSGALG00000048475, FLNA, MYL10, and IL18 were enriched in terms of Salmonella infection." (PMID 37761904, 2023).
Tauopathies (2 papers, 2023 to 2025). "It has previously been shown that the FLNA protein may be involved in the pathogenesis of various tauopathies." (PMID 40141747, 2025). "Collectively, our data indicated that in Tauopathies, FLNA could contribute to Tau pathology by acting on Tau and annexin A2." (PMID 36399251, 2023). "Collectively, our data indicated that in Tauopathies, FLNA could contribute to Tau pathology by acting directly on Tau and indirectly through its interacting partners." (PMID 36399251, 2023). "However, the contribution of FLNA to Tau aggregation in Tauopathies remains controversial." (PMID 36399251, 2023). "It is also known that FLNA and ANXA2 are involved in altering the structure of F-actin, which may also be important for the pathogenesis of tauopathies in general." (PMID 40141747, 2025).
triple-negative breast carcinoma (2 papers, 2021 to 2022). An invasive breast carcinoma which is negative for expression of estrogen receptor (ER), progesterone receptor (PR), and human epidermal growth factor receptor 2 (HER2). "This pathway has been also involved in androgen induced migration of triple negative breast cancer cells but not in PC cells, where the Fak phosphorylation, the activation of cell motility and invasion appear to be strictly dependent on the formation of the AR/FlnA complex." (PMID 35011576, 2021).
viral infection (2 papers, 2010 to 2025). "Interestingly, ORF45 deficiency, Filamin A knockout and S2152A knockin dramatically decreases KSHV de novo infection and cell-contact dependent viral infection in adherent cells." (PMID 41284726, 2025). "Subsequently, ORF45-induced Filamin A phosphorylation facilitated KSHV de novo infection and cell-contact mediated viral infection." (PMID 41284726, 2025). "Our results show that both ORF45 and Filamin A phosphorylation are important of both KSHV de novo infection of cell-free virion particles and cell-contact viral infection from cells undergoing lytic replication." (PMID 41284726, 2025). "Therefore, ORF45-mediated Filamin A phosphorylation promotes KSHV de novo infection and cell-contact mediated viral infection." (PMID 41284726, 2025). "FLNA is to be as an adaptor protein that links HIV-1 receptors to the actin cytoskeleton remodeling machinery, which may facilitate virus infection." (PMID 20504321, 2010). "After these cells were infected with Bac16 or STOP45 viruses for 24 h, the primary infection of Bac16 viruses greatly induced Filamin A phosphorylation while STOP45 viral infection weakly increased it in WT cells, and no Filamin A phosphorylation was observed in either Filamin A KO or KI cells." (PMID 41284726, 2025).
X-linked periventricular heterotopia (2 papers, 2009 to 2024). "X-linked periventricular heterotopias (PVHN) is caused by a mutation in the gene encoding filamin A (FLNA) on chromosome Xq28." (PMID 38201421, 2024). "The FLNA gene is located on the X-chromosome and mutations leading to loss of FLNa expression or function were later identified as causative in X-linked periventricular heterotopia (PVH) in heterozygous females, revealing a role for FLNa in neuronal migration." (PMID 19915675, 2009).
adrenocortical tumours (1 paper, 2023). "Overall these data suggest that FLNA may be a cancer suppressor factor in adrenocortical tumours." (PMID 38068896, 2023).
AIDS (1 paper, 2010). A syndrome resulting from the acquired deficiency of cellular immunity caused by the human immunodeficiency virus (HIV). "For example, the host protein interaction net such as VCL - TLN1 - actin, cytoplasmic 2(ACTG1) - FLNA was found to interact with nef and pol (HIV function proteins), and be substantially up-regulated in HIV/AIDS patients." (PMID 20222986, 2010).
aneurysm (1 paper, 2018). Bulging or ballooning in an area of an artery secondary to arterial wall weakening. "Mutations in FLNA may result in cardiac valvular dystrophy, aneurysms, cardiac defects and neurological dysfunction." (PMID 30235220, 2018).
asthma (1 paper, 2025). "TAGLN increased (p < 0.01) and FLNA expression decreased (p < 0.05, n = 5 each group) in smooth muscle from the trachea in asthma model guinea pigs compared to controls." (PMID 40980809, 2025). "Based on immunohistochemistry data, the interactomes related to the expression of MYH11, MYL9, ACTG1, ACTA2, ACTB, TAGLN, and FLNA in the bronchial smooth muscle of guinea pigs in an asthma model were generated." (PMID 40980809, 2025). "This study confirmed the expression of peptides corresponding to ACTA2, ACTB, ACTG1, MYH11, FLNA, MYL9, and TAGLN in both control guinea pigs and the asthma model." (PMID 40980809, 2025).
autism (1 paper, 2024). Persistent deficits in social interaction and communication and interaction as well as a markedly restricted repertoire of activity and interest as well as repetitive patterns of behavior. "Mutations in the FLNA gene have been found to disrupt critical physiological mechanisms and have been associated with various medical conditions, such as autism." (PMID 39194544, 2024).
Autoimmunity (1 paper, 2022). The occurrence of an immune reaction against the organism's own cells or tissues. "Again, protein molecules from the gut microbiome such as filamin A (FLNA) and N-Acetyl-glucosamine-6-sulfatase (GNS) can potentiate and induce autoimmunity in RA through molecular mimicry." (PMID 36329845, 2022).
B-cell lymphomas (1 paper, 2015). "An unexpected finding in this study was that FilGAP and /or FLNa scores were positively correlated with cytoplasmic Rac1 scores in B-cell lymphomas, which is inconsistent with idea that the FilGAP/FLNa system suppresses Rac1 activity 9–11." (PMID 25641953, 2015). "Although we are presently unable to provide an appropriate explanation for this observation, it appears that the regulatory mechanism for Rac1/FilGAP/FLNa axis may be very complex in B-cell lymphomas." (PMID 25641953, 2015). "Average FilGAP scores were significantly higher in B-cell lymphomas than those in PTCL, while FLNa, integrin β2, and ECT2 scores were significantly higher in PTCL than those in FL." (PMID 25641953, 2015).
benign prostate tumors (1 paper, 2022). "Specifically, in metastatic prostate cancer, cytoplasmic FLNA is phosphorylated at S2152, which prevents its cleavage at the hinge region to the 90-kDa fragment, whereas in less aggressive or benign prostate tumors, the 90-kDa FLNA is found in the nucleus." (PMID 35957887, 2022).
breast fibroepithelial tumors (1 paper, 2021). "The results showed that PAF did not carry the NAB2-STAT6 gene fusion in SFT or the genetic changes in breast fibroepithelial tumors, such as MED2, RARA, and FLNA." (PMID 34350112, 2021).
Cantrell syndrome (1 paper, 2017). "We observed defects in rib and sternum midline closure leading to thoracoabdominal schisis in FlnA+Fmn2 knockout mice, reminiscent of the pentalogy of Cantrell syndrome." (PMID 29240780, 2017).
Chronic constipation (1 paper, 2022). Constipation for longer than three months with fewer than 3 bowel movements per week, straining, lumpy or hard stools, and a sensation of anorectal obstruction or incomplete defecation. "It has been suggested that Xq28 duplications involving the ID-associated filamin A gene (FLNA; 300017) contribute to the presence of chronic constipation, as FLNA point mutations have been found in families with pseudointestinal obstruction." (PMID 35313898, 2022).
chronic obstructive lung disease (1 paper, 2024). "Other FLNA variants are associated with other extracerebral manifestations besides PVNH, like chronic obstipation, chronic obstructive lung disease, and platelet abnormalities." (PMID 39776704, 2024).
chronic respiratory failure (1 paper, 2023). "Following the successful MSC-based treatment of a life-threatening respiratory syndrome associated with the filamin A (FLNA) gene mutation in a child, we performed this therapeutic approach as a rescue therapy in a child with chronic respiratory failure associated with SP-C dysfunction." (PMID 36670712, 2023).
coagulopathies (1 paper, 2022). "Data from platelets further underscore how FLNA integrates signaling pathways between the plasma membrane and the actin cytoskeleton, and also provide an explanation for the coagulopathies associated with FLNA gene variants." (PMID 36605989, 2022).
colorectal adenoma (1 paper, 2025). An adenoma that arises from the colon or rectum. "Furthermore, FLNA has been reported to be significantly downregulated at the transcriptional level in human colorectal adenoma tissues, with aberrant expression also observed in colorectal tumor tissues." (PMID 41367384, 2025).
corticotropinomas (1 paper, 2025). "In summary, FLNA emerges as a novel molecular marker for various tumor types, including corticotropinomas, due to its involvement in receptor dynamics and signaling tumoral cells." (PMID 40364036, 2025).
diffuse large B-cell lymphoma (1 paper, 2015). "In this study, we investigated the expression of FilGAP, with reference to the status of its associated molecules, including FLNa, integrin β2, epithelial cell transforming factor 2 (ECT2), and Rac1, in FL, diffuse large B-cell lymphoma (DLBCL), and peripheral T-cell lymphoma (PTCL)." (PMID 25641953, 2015).
Dravet syndrome (1 paper, 2023). "A gene-based collapsing analysis highlighted an increased variant burden in CHD2, FLNA and TSC1 (P < 0.05) in Dravet syndrome compared with GEL SCN1A controls that was not significant after correction for multiple comparisons." (PMID 37006128, 2023).
embryonic cancers (1 paper, 2020). "We tested the expression of FLNA, FLNB and FLNC in different germ cell cancer tissues using an Affymetrix expression array analysis and found abundant expression of FLNA, in particular in seminonas, embryonic cancers and teratomas." (PMID 33266100, 2020).
Emery-Dreifuss muscular dystrophy (1 paper, 2014). Emery-Dreifuss muscular dystrophy (EDMD) is characterized by muscular weakness and atrophy, with early joint contractures and cardiomyopathy. "One of these (HsInv0389) inverts the FLNA and EMD genes and has been associated to a deletion causing Emery-Dreifuss muscular dystrophy." (PMID 24651690, 2014).
endometrial cancer (1 paper, 2018). Primary or metastatic malignant neoplasm involving the endometrium (mucous membrane that lines the endometrial cavity). "Global gene expression analyses demonstrated a ligand-dependent upregulated expression of filamin-A (FLNA), a gene that encodes an actin filament cross-linking protein, in both endometrial cancer cell types." (PMID 29615978, 2018). "Western blots revealed that FLNA is basally expressed in both ECC-1 and USPC-1 endometrial cancer cells." (PMID 29615978, 2018). "Microarray gene expression analyses showed a significant ligand-dependent upregulated expression of FLNA in ECC-1 and USPC-1 endometrial cancer cells." (PMID 29615978, 2018).
fibrosis (1 paper, 2017). the formation of excess fibrous connective tissue in an organ or tissue in a reparative or reactive process. "It indicated that Filamin A could serve as a possible marker for HCS activationact as α-SMA protein, further validated by immunohistochemistry in CCl4-induced fibrosis liver paraffin tissue section and by immunofluorescence in cultured murine HSCs in vitro." (PMID 28322315, 2017).
haemophilia A (1 paper, 2018). "Structural changes in filamin-A architecture caused by X-linked inheritance were found to cause myxomatous valvular dystrophy of the mitral and/or aortic valve combined with haemophilia A." (PMID 29486707, 2018).
in situ carcinoma (1 paper, 2013). A malignant epithelial neoplasm which is confined to the epithelial layer without evidence of further tissue invasion. "Although the question of whether the filamin-A levels witnessed in these cancer tissues were inclusive of surrounding ECM among the in situ carcinoma remains elusive, this study suggests that loss of filamin-A enhances FAK turnover, which results in the disrupting cancer cell attachment to the EMC." (PMID 23388158, 2013).
infertile (1 paper, 2015). "In our previous study, random distribution and depletion of H3K9ac interaction in many loci (for example, CTSD, FLNA, MCF2L, PLXNA3, SG3GLB2, TH) of infertile men sperm have been confirmed." (PMID 25806092, 2015).
influenza (1 paper, 2020). An acute viral infection of the respiratory tract, occurring in isolated cases, in epidemics, or in pandemics; it is caused by serologically different strains of viruses (influenzaviruses) designated A, B, and C, has a 3-day incubation period, and usually lasts for 3 to 10 days. "Due to the conserved nature of the FLNA-NP interaction, we prove FLNA as a novel and attractive target for the development of anti-influenza drug." (PMID 33101257, 2020). "Our results reveal FLNA to be a host factor with antiviral potential hitherto unknown to be involved in the IAV replication cycle thus, opening new possibilities of FLNA-NP interaction as a candidate anti-influenza drug development target." (PMID 33101257, 2020).
Klinefelter syndrome (1 paper, 2023). A sex chromosome disorder caused by the presence of an extra X chromosome in the male karyotype. "First, two of them had associated congenital anomalies and prolonged hospitalization during the first month of life that could possibly contribute to the disturbed motor performance: Filamin A deficiency and Klinefelter syndrome." (PMID 37326640, 2023).
Leukoencephalopathy (1 paper, 2021). This term describes abnormality of the white matter of the cerebrum resulting from damage to the myelin sheaths of nerve cells. "Additionally, further analyses of the interaction between mutated C11ORF73 proteins and Filamin A may allow us to understand whether and how this interaction is actually responsible for the molecular and cellular pathological phenotypes associated with infantile leukoencephalopathy." (PMID 33535532, 2021).
Lissencephaly (1 paper, 2015). A spectrum of malformations of cortical development caused by insufficient neuronal migration that subsumes the terms agyria, pachygyria and subcortical band heterotopia. "FLNA and Lis1 have been identified as causative genes for PVH and lissencephaly, respectively, and both knockout of FLNA and Lis1 heterodeficiency show neuronal migration defects." (PMID 26500496, 2015).
low grade glioma (1 paper, 2025). A grade I or grade II glioma arising from the central nervous system. "Other relevant pathways in cancer, such as focal adhesion, cytoskeleton regulation, and chemokine signalling (VCL, THBS1-4, FLNA, LAMA2/4/5, HSPG2), might also be influenced indirectly by changes in the WWOX/HIF1A ratio, potentially impacting the overall prognosis of low-grade glioma patients." (PMID 41007296, 2025).
male infertility (1 paper, 2020). The inability of the male to effect fertilization of an ovum after a specified period of unprotected intercourse. "Other proteins that interact with filamin A, include the AR and nephrocystin 4 (NPHP4) and we found in HF conditions, a significant decrease in filamin interacting protein NPHP4, important for cytoskeleton signalling, cell adhesion and ciliary development and associated with human male infertility." (PMID 32678325, 2020).
Miscarriage (1 paper, 2022). A pregnancy that ends at a stage in which the fetus is incapable of surviving on its own, defined as the spontaneous loss of a fetus before the 22th week of pregnancy. "Therefore, it is assumed that the previous miscarriages were caused by the FLNA variant, which is often lethal in males, as FLNA plays a critical role in human embryonic development." (PMID 36509760, 2022).
Moyamoya disease (1 paper, 2023). Moyamoya disease (MMD) is a rare intracranial arteriopathy involving progressive stenosis of the cerebral vasculature located at the base of the brain causing transient ischemic attacks or strokes. "Remarkably, FLNA has been recently identified as a possible second-hit gene promoting moyamoya disease-like vascular formation in a PVNH patient, and it was associated with Ring Finger protein 213 (RNF213) p.R4810K variant, the most common MMA polymorphism." (PMID 37446373, 2023).
myalgic encephalomyelitis (1 paper, 2022). "For example, in patients with myalgic encephalomyelitis and chronic fatigue syndrome, which are challenging to diagnose, the amount of EVs in plasma increases, and actin network proteins such as talin-1 and filamin A, which are characteristically encapsulated, may serve as biomarkers." (PMID 36557150, 2022).
myeloid leukemia (1 paper, 2020). A clonal proliferation of myeloid cells and their precursors in the bone marrow, peripheral blood, and spleen. "Furthermore, Filamin A knockdown or ASB2α-mediated Filamin A degradation enhances adhesion of myeloid leukemia cells to fibronectin." (PMID 33330471, 2020).
myocarditis (1 paper, 2013). Myocarditis is a condition that is characterized by inflammation of the heart muscle (myocardium). "In contrast to filamin A and filamin B, the high expression of filamin C in myocytes suggests that filamin C represents a sensitive and specific marker of the subclinical myocarditis that accompanies KD." (PMID 23281308, 2013).
obstructive lung disease (1 paper, 2015). "More recently, progressive obstructive lung disease has been documented as a rare clinical manifestation in FLNA mutation carriers." (PMID 26471271, 2015).
obstructive uropathy (1 paper, 2020). "Past publications have broadly noted “obstructive uropathy” or “genitourinary abnormalities” in rare male patients who died neonatally with FLNA mutations." (PMID 32085749, 2020).
omphalocele (1 paper, 2023). Omphalocele is an embryopathy classified in the group of abdominal celosomias and is characterized by a large hernia of the abdominal wall, centered on the umbilical cord, in which the protruding viscera are protected by a sac. "Based on the clinical features of fetuses, including hygroma colli, midline structure dysplasia of omphalocele or thoracoceloschisis, abnormal lower limbs and partial facial features, and genetic information with FLNA mutation, we considered the diagnosis of the proband as MNS." (PMID 36734119, 2023).
OPD) spectrum disorders (1 paper, 2012). "FLNA missense mutations cause four genetic syndromes belonging to the otopalatodigital (OPD) spectrum disorders." (PMID 22369496, 2012). "Although heterozygotes for FLNA mutations causing OPD spectrum disorders showed a pronounced imbalance in X-inactivation mosaicism in leukocytes this does not appear to be true of heterozygotes for mutations causing PVNH." (PMID 22369496, 2012).